CIAPIN1 (cytokine induced apoptosis inhibitor 1)
Description:
Component of the cytosolic iron-sulfur (Fe-S) protein assembly (CIA) machinery required for the maturation of extramitochondrial Fe-S proteins. Part of an electron transfer chain functioning in an early step of cytosolic Fe-S biogenesis, facilitating the de novo assembly of a [4Fe-4S] cluster on the scaffold complex NUBP1-NUBP2. Electrons are transferred to CIAPIN1 from NADPH via the FAD- and FMN-containing protein NDOR1. NDOR1-CIAPIN1 are also required for the assembly of the diferric tyrosyl radical cofactor of ribonucleotide reductase (RNR), probably by providing electrons for reduction during radical cofactor maturation in the catalytic small subunit (By similarity). Has anti-apoptotic effects in the cell. Involved in negative control of cell death upon cytokine withdrawal. Promotes development of hematopoietic cells (By similarity).
Synonyms: PRO0915; CIAE2; Anamorsin; DRE2
Tractability: Small molecule: it has a high-quality binding pocket. PROTAC: ubiquitination databases record sites on it; its protein half-life has been measured.
Gene: Protein-coding gene on chromosome 16 (57,428,177 to 57,447,420, reverse strand). Ensembl gene ENSG00000005194.
Subcellular location: Cytoplasm; Nucleus; Mitochondrion intermembrane space
Subcellular location (Human Protein Atlas): Mitochondria; Nucleoplasm
Pathways (Reactome):
Metabolism: Cytosolic iron-sulfur cluster assembly
Gene Ontology:
Molecular function: 2 iron, 2 sulfur cluster binding; iron ion binding; protein binding; electron transfer activity; iron-sulfur cluster binding
Biological process: cellular response to oxidative stress; iron-sulfur cluster assembly; negative regulation of apoptotic process; hemopoiesis
Cellular component: cytoplasm; cytosol; cytosolic [4Fe-4S] assembly targeting complex; mitochondrial intermembrane space; mitochondrion; nucleolus; nucleoplasm; nucleus
Genetic constraint (gnomAD): Loss-of-function variants: 12 observed, 28.29 expected, observed/expected ratio (o/e) 0.42, 90% interval 0.27 to 0.69. The upper end of that interval is the gene's LOEUF score, 0.69, which puts it in group 2 of 6, group 1 being the genes least tolerant of losing a copy. Missense variants: 290 observed, 358.13 expected, observed/expected ratio (o/e) 0.81, 90% interval 0.74 to 0.89. Synonymous variants: 127 observed, 138.33 expected, observed/expected ratio (o/e) 0.92, 90% interval 0.79 to 1.06.
Homologues: Orthologues: chimpanzee CIAPIN1 (99% identical), macaque CIAPIN1 (98% identical), pig CIAPIN1 (89% identical), guinea pig CIAPIN1 (88% identical), dog CIAPIN1 (87% identical), mouse Ciapin1 (81% identical), rat Ciapin1 (81% identical), rabbit CIAPIN1 (72% identical), tropical clawed frog ciapin1 (60% identical), zebrafish ciapin1 (55% identical), Drosophila melanogaster CIAPIN1 (37% identical), Caenorhabditis elegans T20B12.7 (29% identical).
Diseases named in the same sentence as CIAPIN1 in open-access papers:
CIAPIN1 is named in the same sentence as 35 diseases in open-access papers, as found by Europe PMC text mining. Sharing a sentence is not in itself a finding about the gene and the disease. The quoted sentences say what the papers report.
colorectal cancer (6 papers, 2010 to 2022). A primary or metastatic malignant neoplasm that affects the colon or rectum. "Furthermore, the decrease in CIAPIN1 expression is significantly associated with a longer survival time of diffuse large B cell lymphoma, colorectal cancer, pancreatic cancer, and non-small-cell lung carcinoma." (PMID 35807116, 2022). "The aim of this study was to determine the prognostic impact of CIAPIN1 in 273 colorectal cancer (CRC) samples and to investigate the CIAPIN1 expression in CRC cell lines after inducing differentiation." (PMID 20815902, 2010). "To accurately quantify CIAPIN1 expression level changes in colorectal carcinomas, we performed Western blot analysis in 40 CRC tissues and matched normal tissues." (PMID 20815902, 2010). "However, decreased expression of CIAPIN1 correlated with poor prognosis in patients with other types of cancers, such as colorectal cancer and esophageal squamous cell carcinoma." (PMID 31645899, 2019). "In recent studies, the significance of CIAPIN1 has been identified in tumors such as esophageal cancer and colorectal cancer; however, the correlations were detected between the expression level of CIAPIN1 in both the nucleus and cytoplasm, and tumor clinicopathological features." (PMID 22713669, 2012). "In addition, we investigated the expression of CIAPIN1 after inducing differentiation in colorectal cancer cell lines." (PMID 20815902, 2010). "However, studies on the role of CIAPIN1 in colorectal cancer were still unavailable." (PMID 20815902, 2010).
breast carcinoma (5 papers, 2012 to 2025). "An inverse association between miRNA-143 and CIAPIN1 protein expression levels has been observed in a number of breast cancer cell lines." (PMID 31979312, 2020). "CIAPIN1 gene silencing enhanced the sensitivity of tumor cells to doxorubicin in drug-resistant breast cancer xenografts in this nude mouse model." (PMID 35807116, 2022). "Then we successfully interfered with RNA translation by the infection of siRNA of CIAPIN1 into MCF7/ADM breast cancer cell lines through a lentivirus, and the expression of the target gene was significantly inhibited." (PMID 22717413, 2012). "Studies suggest that CIAPIN1 overexpression promotes breast cancer by regulating cell cycle and DNA replication, while DBNDD1 hypomethylation may contribute to tumor progression by affecting DNA synthesis or damage repair." (PMID 41048937, 2025). "Meanwhile we also confirmed that performing RNAi on CIAPIN1 gene by a viral transfection approach may effectively reverse MDR of breast cancer, which provides a new way for improving therapeutic effects." (PMID 22717413, 2012). "However, until now no article has reported whether CIAPIN1 is associated with the mechanism of MDR in breast cancer cells or not." (PMID 22717413, 2012). "The aim of this study was to explore the relationship between CIAPIN1 and MDR of breast cancer cells." (PMID 22717413, 2012). "Using MDA-MB-231 and MDA-MB-468 breast cancer cells with altered CST/SM4 levels, RNA sequencing and functional analyses revealed that overproduction of the CST/SM4 significantly downregulated BOLA2, a gene in the CIAPIN1 pathway involved in apoptosis." (PMID 41465298, 2025).
lymph node metastasis (5 papers, 2010 to 2022). "In CCA patients, higher serum CIAPIN1 level was significantly associated with lymph node metastasis (p = 0.024) and shorter overall survival time (p = 0.001, Kaplan–Meier test)." (PMID 34201138, 2021). "In particular, the higher serum level of CIAPIN1 was associated notably with lymph node metastasis and shorter overall survival time." (PMID 34201138, 2021). "As can be seen, high CIAPIN1 expression was significantly correlated with lymph node metastasis (p = 0.010), intraductal invasion (p = 0.048), and overall survival time (p = 0.013)." (PMID 35807116, 2022). "Chi-square analysis revealed that high CIAPIN1 expression was significantly correlated with lymph node metastasis (p = 0.024) and overall survival (OS) (p = 0.037)." (PMID 34201138, 2021). "We next performed Cox’s univariate and multivariate hazard regression model to identify the independent factors that were significantly associated with OS to examine the effect of the covariates including the patients’ CIAPIN1 expression level, lymph node metastasis, age, sex, and other factors." (PMID 34201138, 2021). "In addition, upregulation of CIAPIN1 is related to lymph node metastasis." (PMID 35807116, 2022). "A further study with large sample size is needed to unravel the correlation between lymph node metastasis and CIAPIN1 expression, and also to identify whether CIAPIN1 can be a precise and reproducible prognostic marker and metastasis indicator for CCA patients." (PMID 35807116, 2022). "Furthermore, CIAPIN1 expression was higher in CCA tissues of patients with lymph node metastasis." (PMID 35807116, 2022). "In particular, the serum CIAPIN1 level was significantly higher in CCA patients with lymph node metastasis than those without metastasis." (PMID 35807116, 2022). "The results showed that the serum CIAPIN1 level was recognized as an independent prognostic factor for the overall survival of CCA patients (HR = 1.88, 95% CI: 1.123–3.141; p = 0.016), which was the same as lymph node metastasis." (PMID 34201138, 2021). "Our data showed that the serum CIAPIN1 level was significantly higher in CCA patients with lymph node metastasis than in the patients without metastasis." (PMID 34201138, 2021).
gastric cancer (4 papers, 2010 to 2022). A primary or metastatic malignant neoplasm involving the stomach. "CIAPIN1 was also proved to exert a pivotal effect on some malignant cancers such as gastric cancer, hepatocellular carcinoma, and renal cancer." (PMID 31093311, 2019). "Immunohistochemical studies had shown that there was low expression of CIAPIN1 in gastric cancer, but the expression in the corresponding adjacent tissues and normal tissues was high." (PMID 20815902, 2010). "We previously confirmed that CIAPIN1 expression in gastric cancer, liver cancer and clear cell renal cell carcinoma (CCRCC) was down-regulated compared to their adjacent normal tissue counterparts." (PMID 20815902, 2010). "Previous study of our group had shown that CIAPIN1 was involved in the regulation of multidrug resistance (MDR) of gastric cancer cells." (PMID 20815902, 2010). "We also found that the expression of CIAPIN1 was higher in the cells of gastric cancer SGC7901/VCR than in SGC7901 cells." (PMID 20815902, 2010). "Our group also demonstrated that CIAPIN1 inhibited gastric cancer and CCRCC cell proliferation, as well as cell-cycle progression by down-regulating CyclinD1 and up-regulating P27." (PMID 20815902, 2010). "Up-regulation of CIAPIN1 expression in gastric cancer cell lines demonstrated that CIAPIN1 might be involved in the regulation of gastric cancer cell proliferation and apoptosis." (PMID 20815902, 2010). "The cytokine-induced anti-apoptotic molecule (CIAPIN1) had been found to be a differentially-expressed gene involved in a variety of cancers, and it was also considered as a candidate tumour suppressor gene in gastric cancer, renal cancer and liver cancer." (PMID 20815902, 2010). "CIAPIN1 siRNA could also significantly down-regulate the expression of Bcl-2, and up-regulate the expression of Bax but not that of PTEN in gastric cancer cells." (PMID 20815902, 2010).
hepatocellular carcinoma (3 papers, 2012 to 2023). A malignant tumor that arises from hepatocytes. "CIAPIN1 plays key roles in cancers such as gastric, hepatocellular carcinoma, and renal cancers and it has been suggested that CIAPIN1 has an important role in cancer therapy." (PMID 37445656, 2023). "Consistently, CIAPIN1 has also been found to be elevated in hepatocellular carcinoma and diffuse large B cell lymphoma." (PMID 22713669, 2012). "Moreover, CIAPIN1 has been demonstrated to be a critical molecule involved in tumor aggressiveness and may represent a prognostic marker for patient outcome in several types of cancer, such as hepatocellular cancer and leukemia." (PMID 22713669, 2012).
non-small cell lung carcinoma (3 papers, 2019 to 2022). A group of at least three distinct histological types of lung cancer, including non-small cell squamous cell carcinoma, adenocarcinoma, and large cell carcinoma. "In contrast to our results, in the case of non-small-cell lung carcinoma (NSCLC), CIAPIN1 overexpression inhibited cell migration and invasion and suppressed the expression of MMPs and EMT-associated markers." (PMID 35807116, 2022).
clear cell renal cell carcinoma (2 papers, 2019). "Enhanced expression of CIAPIN1 resulted in suppression of clear renal cell carcinoma-derived cells G1-phase arrest as revealed by decreased levels of cyclin (D1, E), CDK, p-Rb, and VEGF, as well as increased levels of p27Kip1." (PMID 30637589, 2019).
epithelial ovarian cancer (2 papers, 2012 to 2022). "Overexpression of CIAPIN1 was reported in epithelial ovarian cancer and metastatic ovarian serous carcinoma." (PMID 35807116, 2022).
lung carcinoma (2 papers, 2019). "Our results revealed high CIAPIN1 expression in lung cancer, and CIAPIN1 was closely associated with the prognosis of NSCLC patients." (PMID 31093311, 2019). "As CIAPIN1 was a potential target gene of miR-195-5p, we further investigated the expression of CIAPIN1 in lung cancer tissues by performing meta-analysis using public microarray datasets from Oncomine database." (PMID 30637589, 2019). "Meta-analysis based on Oncomine database showed CIAPIN1 was significantly up-regulated in human lung cancer tissues." (PMID 30637589, 2019). "Initially, we investigated the expression of CIAPIN1 in lung cancer with the purpose of seeking the working molecular mechanisms of NSCLC metastatic potential and ultimately finding a novel molecular marker for early diagnosis and prognosis of NSCLC patients." (PMID 31093311, 2019). "In the following study, we successfully altered CIAPIN1 expression in A549 cells to explore the role of CIAPIN1 in lung cancer cells' migration and invasion." (PMID 31093311, 2019). "In our study, we tried to investigate the correlation of CIAPIN1 and lung cancer patients' prognosis, as well as the role of CIAPIN1 in A549 cells' migration and invasion." (PMID 31093311, 2019). "The report indicated that CIAPIN1 might be considered a candidate tumor suppressor gene in CCRCC, while effects of CIAPIN1 on lung cancer remain unknown." (PMID 31093311, 2019). "Our present findings suggest that CIAPIN1 may not only be a useful indicator for predicting the outcome of lung cancer patients but also be an effective therapeutic target for lung cancer." (PMID 31093311, 2019). "All the work provided a potential management by which CIAPIN1 might be crucial on the suppression of lung cancer metastasis." (PMID 31093311, 2019). "These analyses suggested that CIAPIN1 might play a potential carcinogenesis in lung cancer." (PMID 30637589, 2019). "As CIAPIN1 was overexpressed in lung cancer and might be a direct functional target of miR-195-5p in NSCLC cells, we next performed loss-of-function assays in A549 cells to further examine the biological function of CIAPIN1." (PMID 30637589, 2019). "Moreover, cancerous lung carcinoma tissues showed lower positive rate of CIAPIN1 as compared to that in the than that in the noncancerous tissues." (PMID 30637589, 2019).
asthma (1 paper, 2025). "Cytokine‐induced apoptosis inhibitor 1 (CIAPIN1) is an essential anti‐apoptotic protein; however, its role and associated molecular pathways in asthma remain largely unexplored." (PMID 40338178, 2025). "Our data revealed that CIAPIN1 levels were elevated and positively associated with asthma severity." (PMID 40338178, 2025). "Pearson's correlation analysis was conducted to examine the relationship between CIAPIN1 expression levels and the clinicopathological characteristics of asthma patients." (PMID 40338178, 2025). "Enzyme‐linked immunosorbent assay (ELISA) analysis revealed that serum levels of CIAPIN1 were significantly higher in patients with asthma than in healthy controls (p < 0.0001)." (PMID 40338178, 2025). "Additionally, reducing CIAPIN1 expression may be a promising therapeutic strategy for alleviating asthma." (PMID 40338178, 2025). "CIAPIN1 plays a role in the PI3K/AKT and JAK2/STAT3 signaling pathways, making it a promising candidate for therapeutic interventions to manage asthma." (PMID 40338178, 2025).
Fanconi anemia complementation group D2 (1 paper, 2020). Fanconi anemia caused by mutations of the FANCD2 gene. "Other factors that negatively regulate the apoptotic process (Fanconi anemia complementation group D2 and cytokine-induced apoptosis inhibitor 1) were also upregulated at 48 h." (PMID 33261663, 2020).
lung adenocarcinoma (1 paper, 2019). A carcinoma that arises from the lung and is characterized by the presence of malignant glandular epithelial cells. "We also showed increased CIAPIN1 mRNA expression in lung adenocarcinoma tissues compared with normal tissues by selecting three datasets." (PMID 30637589, 2019). "Oncomine microarray database showed that CIAPIN1 is expressed in high levels in lung adenocarcinoma tissues compared to normal lung tissues." (PMID 30637589, 2019).
oral cancer (1 paper, 2020). "CIAPIN1 was found to be up‐regulated in invasive oral cancer in our study, and the role of CIAPIN1 in oral cancer invasion remains unknown." (PMID 32672400, 2020).